BACE1 (beta-secretase 1)
Diseases named in the same sentence as BACE1 in open-access papers (continued):
Sharing a sentence is not in itself a finding about the gene and the disease.
Cognitive impairment (continued). "Cognitive impairment was found to be accelerated by some agents that suppress the generation of nascent Aβ, including inhibitors of the γ-secretase and the BACE1." (PMID 32824102, 2020). "Previous studies have reported that tolfenamic acid alleviated cognitive deficits and downregulated the expression of BACE1, APP, and phosphorylated tau in APP transgenic mice." (PMID 31049134, 2019). "In this study, we observed that EA intervention on AD mice reduced BACE1 through downregulating APP cleavage to ameliorate cognitive impairments." (PMID 31223308, 2019). "In a previous study, young WT C57BL/6 mice consuming a high‐fat, high‐cholesterol (HFC) diet showed neuroinflammation and cognitive deficit as well as up‐regulation of BACE1 transcription." (PMID 30411846, 2019). "This is supported by the studies showing either deletion or inhibition of BACE1 precludes Aβ pathology and cognitive impairment in AD mouse model." (PMID 29961672, 2018). "Ethanol exposure of mice for 4 weeks increased APP levels and BACE1 expression, promoted Aβ production, increased plaque deposition, and worsened cognitive deficits." (PMID 29759078, 2018). "Blocking GRs with the GR antagonist mifepristone for only 3 days normalised the elevated plasma CORT levels, reduced Aβ and BACE1 levels, and rescued the cognitive impairments in 12-month-old ELS-APPswe/PS1dE9 mice." (PMID 29491368, 2018). "For example, MgT treatment was reported to stabilize β-secretase (BACE-1) expression and to reduce soluble APP and β-C-terminal fragments, which prevented and reversed cognitive deficits and synaptic loss in APP/PS1 transgenic mice." (PMID 29899688, 2018). "Conversely, a previous study reported that BACE1 inhibitor treatment repairs pathophysiology and cognitive deficits in APP23xPS45 mice even when initiated after the development of extensive Aβ pathology." (PMID 29327084, 2018). "Alterations in specific miRNA levels can upregulate expression and stability of BACE1 protein, which in turn contributes to synaptic and cognitive deficits." (PMID 28851397, 2017). "Together, our results suggest that PM2.5 aspiration suppresses miR-574-5p expression by augmenting NF-κB activity, which then facilitates BACE1 activation and results in synaptic and cognitive impairment." (PMID 28851397, 2017). "Expression of APP and BACE1 has been shown to be increased in neuroinflammation and to be involved in cognitive impairment." (PMID 26373740, 2015). "In transgenic hAPP-mice, increased expression of human BACE1 has been shown to worsen learning and memory deficits, while in normal mice, gene knock-in of hBACE1 generated AD-relevant cognitive impairment." (PMID 26274614, 2015). "On the basis of these data, we proposed that EA upregulates SIRT1-PPARγ- PGC-1, which represses BACE1 expression, thereby reducing Aβ production and consequently improving cognitive deficits in an AD animal model." (PMID 26283960, 2015). "Current BACE1 inhibitor trials have enrolled mild and moderate AD or mild cognitive impairment (MCI), the latter of which progresses to AD at a rate of ~10-15% per year." (PMID 25621019, 2014). "Memoquin acts as an acetylcholinesterase inhibitor, BACE1 inhibitor, and antioxidant, and it has been reported to improve scopolamine- and Aβ-induced cognitive impairment." (PMID 24707311, 2014). "Other studies reported serious morbid effects, like early death, reduced size, and cognitive deficits in BACE1-knockout animals, which suggest the potential liabilities of BACE1 inhibition." (PMID 23133641, 2012). "Recent studies have shown that Aβ generation, amyloid pathology, electrophysiological dysfunction, and cognitive deficits become abrogated when BACE1−/− mice are bred with APP transgenic mice." (PMID 22701746, 2012). "We propose here that cognitive impairment by BACE1 inhibitors may be a corollary of a higher function of BACE1 related to proper sleep regulation." (PMID 41266616, 2026).
Cognitive impairment (continued). "Furthermore, modulation of the miR‐32533/CREB5 axis ameliorated or worsened cognitive impairment by inhibiting or amplifying Aβ overproduction through the BACE1‐involved amyloidogenic and ADAM10‐involved non‐amyloidogenic pathways." (PMID 39840513, 2025). "Reduced miR-574-5p expression, leading to altered binding to the 3′UTR of BACE1, may contribute to increased BACE1 levels and subsequent synaptic and cognitive impairment following PM2.5 exposure." (PMID 40244238, 2025). "Several human studies conducted on patients with cognitive impairments, including AD, have found that high BACE1 concentrations and activity in the CSF, serum, or plasma are associated with impairments in cognitive functions, as well as neuroimaging features, and brain changes in AD." (PMID 40748886, 2025). "It was reported that MT1 agonists could have a positive impact in reducing amyloidogenesis, and BACE1 activity as well as the cognitive impairment induced by LPS." (PMID 37712973, 2024). "In addition to AChE and COX-2, molecular docking was also performed on other molecular targets linked to cognitive impairment, including GSK-3β, BACE-1, and caspase-3." (PMID 39598743, 2024). "Importantly, BACE1-/- mice are devoid of Aβ amyloidosis, electrophysiological dysfunctions, and cognitive deficits, implying targeted BACE1 inhibition to improve Aβ-mediated loss of cognitive function in humans with AD." (PMID 38077352, 2023). "In pre-clinical trials, BACE1-deficient mice did not exhibit cognitive impairment and accumulation of Aβ plaques." (PMID 33652858, 2021). "There are studies that have detected BACE1 in the CSF of patients with mild cognitive impairment." (PMID 33578866, 2021). "BACE1 is a key enzyme that initiates the formation of Aβ peptides, and studies have shown that the concentration and activity of BACE1 increase in patients with AD and Mild Cognitive Impairment (MCI)." (PMID 35002620, 2021). "Furthermore, the potential cleavage of neuroplastin by BACE1 or other proteases, and its successive cognitive impairment and neurodegeneration, should be addressed." (PMID 34680901, 2021). "Collectively, these results suggest that the inhibition of SIRT2 deacetylation activity may be effective against the cognitive impairment in AD mice, via a reduction of Aβ production by influencing BACE1." (PMID 32700357, 2020). "Aged mice subjected to abdominal surgery displayed increased hippocampal β-amyloid (Aβ) and beta-site APP cleaving enzyme (BACE1) levels in the hippocampus and cognitive impairment, while general anesthesia did not cause such cognitive deficits." (PMID 32046097, 2020). "In fact, BACE1 knockout mice show synaptic plasticity deficits and cognitive impairment." (PMID 33014268, 2020). "Ng/BACE1 levels were elevated in both subjective cognitive decline and mild cognitive impairment compared to healthy controls and can distinguish between depression and AD among patients with similar cognitive deficits, along with the classic AD biomarkers." (PMID 33212853, 2020). "Some studies showed that some compounds could mitigate amyloidogenesis and cognitive impairment via inhibiting the NFKB signal pathway to reduce the activity of BACE1." (PMID 33192455, 2020). "Interestingly, another group reported that the CSF NGR/BACE1 ratio, along with core AD biomarkers, displays good accuracy to distinguish between depression with cognitive impairment and AD dementia." (PMID 33066807, 2020). "All these findings suggested that BACE1 could be a disease-modifying therapeutic target to ameliorate cognitive impairments and alleviate multipathogenesis of APP/PS1 mice." (PMID 31223308, 2019). "Indeed, short-lasting treatment with the glucocorticoid receptor antagonist mifepristone rescued the early life stress-induced cognitive impairments in APPswe/PS1dE9 mice and reduced the Aβ load and BACE1 expression." (PMID 30227888, 2018).
Cognitive impairment (continued). "The compound could (i) mitigate cognitive impairments in the Morris water maze and (ii) decrease BACE1, SK3β activity, p25/CDK5, neuroinflammation, soluble and insoluble Aβ, Aβ, plaques and tau pathologies." (PMID 29243055, 2018). "β-Site amyloid precursor protein (APP) cleaving enzyme 1 (β-secretase, BACE1) is a critical enzyme catalyzing amyloid β (Aβ) peptide generation by cleaving APP, and BACE1 activation is a hallmark of early stage cognitive deficits and plays an important role in progressive conversion to AD." (PMID 28851397, 2017). "Inhibition of mTOR could restore autophagy, reduce BACE1 and Aβ peptides and p-tau aggregates, and attenuate cognitive deficits in AD brains." (PMID 28561773, 2017). "If this hypothesis is correct, restoring or reversing these downregulated miRNAs in animal models following PM2.5 exposure should ameliorate synaptic and cognitive impairment by reducing BACE1 expression." (PMID 28851397, 2017). "If miR-574-5p directly binds to the 3’UTR of BACE1 and miR-574-5p deregulation stimulates BACE1 expression and impairs synaptic and cognitive function in response to PM2.5 aspiration, then overexpression of miR-574-5p should suppress BACE1 elevation and restore synaptic and cognitive impairment." (PMID 28851397, 2017). "Indeed, previous work has shown that the level of BACE1 and Aβ1-42 is positively correlated with cognitive impairment in BCCAO50." (PMID 28205591, 2017). "Finally, we show that EE prevents stress-related cognitive deficits as well as changes in Bace1 expression and DNAm." (PMID 27404286, 2016). "Pharmacodynamic models developed from this future data might assist in the estimation of the level of BACE1 inhibition required to achieve efficacious Aβ reduction for a given cerebral amyloid load and level of cognitive impairment." (PMID 25621019, 2014). "The presentdata together with previous work suggest that BACE1 activity may become elevated at the stage ofmild cognitive impairment, and then decrease over time as disease progresses." (PMID 23224319, 2013). "Although further work is required, these data indicate that a partial suppression of BACE1 may have the most benefit for the earlier phases of Aβ-dependent cognitive impairments." (PMID 18005427, 2007). "In addition, DYRK1A knockdown directly in the hippocampus in Aβ-overexpressing 5xFAD mice significantly attenuated cognitive impairment and neuroinflammatory responses, increased anti-oxidative/anti-inflammatory HO-1 levels, and reduced Aβ pathology by suppressing BACE-1 activity." (PMID 41306975, 2025). "For instance, studies have shown that plasma levels of lncRNA BACE1 were significantly high in AD patients as compared to healthy controls and this increased plasma expression level lncRNA BACE1 levels is positively correlated with severity of cognitive deficits in AD patients." (PMID 39199508, 2024). "BACE1 is not just a biomarker for AD, but it also causes cognitive impairment." (PMID 37821782, 2023). "Furthermore, long-term exposure to high-fat diet increases Bace1 expression in the brain promoting β-amyloid (Aβ) accumulation and cognitive deficits, while treatment with Bace1 inhibitor reduces circulating levels of Aβ1-42 peptide in high-fat diet-induced obese mice." (PMID 35873003, 2022). "Hence, our findings indicated that CPPs-mediated down-regulation of BACE1 activity might be a potential therapeutic strategy for mitigating cognitive deficits in AD." (PMID 32652518, 2020). "Therefore, it is possible that a decrease in specific miRNA levels may upregulate BACE1 expression, resulting in synaptic and cognitive impairment." (PMID 28851397, 2017). "Thus, we propose that the suppression of hippocampal GSK-3β phosphorylation induced by the SM70EE-enhanced BDNF/PI3K/Akt signaling pathway contributes to the inhibition of APP processing by downregulating BACE1 to ameliorate the cognitive disorders induced by an I.C.V. injection of Aβ1–42." (PMID 29137190, 2017).
Cognitive impairment (continued). "BACE1, a key enzyme that generates amyloid β peptide by cleaving APP, is activated in early-stage cognitive deficits and plays a crucial role in AD progression." (PMID 40244238, 2025). "Further, we investigated the relationship between cognitive impairment and the possible roles of serum BDNF, BACE1, VEGF, and GFAP as potential biomarkers for cognitive impairment in people with epilepsy." (PMID 40291844, 2025). "The central aim of our investigation was to assess cognitive impairment and to analyze the relationship between specific biomarkers - BDNF, BACE1, VEGF, GFAP and IL-1β and cognitive dysfunction in adults PWE." (PMID 40291844, 2025). "Anti-BACE1 VHH-B9 demonstrates a high affinity for BACE1 and potential pre-clinical efficiency in APPNL-G-F mouse models, given a single dose relieved AD cognitive deficits and Aβ pathology over 12 months." (PMID 39238639, 2024). "BACE1 activity is increased in brains of patients with AD and mild cognitive impairment (MCI) and plasma levels of BACE1 appear to reflect those in the brains." (PMID 35275540, 2022). "It was found that the up-regulation of miR-29c prevented cognitive impairment in 5xFAD mice, possibly by inhibiting the expressions of DNMT3A, DNMT3B, and BACE1 in the hippocampus." (PMID 34750393, 2021). "Furthermore, the increased BACE1 and mRNA stabilizing antisense (BACE-1-AS) is silenced by NRF2 by linking with antioxidant response elements, whereas the NRF2 deficiency upregulates the BACE-1 and BACE-1-AS expression and Aβ generation thereby enhancing the cognitive impairment." (PMID 34572312, 2021). "The dysregulation of Nav1.1α levels and aberrant cleavage of Navβ2 were contributed to the BACE1 upregulation in cortical neurons, abnormal EEG activity, and cognitive deficits in AD mice." (PMID 32256560, 2020). "Deposition of Aβ amyloid protein is a key mechanism for the development of cognitive impairment, and its main pathway is the hydrolysis of amyloid precursor protein APP into BACE1 (β-secretase 1)." (PMID 32855649, 2020). "Since EGR1 inhibition was also shown to activate BACE1 activity, this calls for further studies into the role of (early life) modulation of EGR1 and its implication in cognitive impairment and AD neuropathology." (PMID 30227888, 2018). "TAT-APPsweBBP treatment reduced BACE1-mediated APP amyloidogenesis both in vitro and in 5XFAD mice, while also reducing cognitive impairments." (PMID 26091071, 2015). "Similar to the miR-29a/29b-1 cluster, miR-107 down-regulation has been observed in mild cognitive impairment (MCI), an early stage of AD; BACE1 has been shown to be a major miR-107 target site." (PMID 24595404, 2014). "Our findings suggest a potential role of IL-6 in the interplay between neuroinflammation and BACE1 levels, although this pathway was not to be altered in SS cognitive impairment." (PMID 40748886, 2025). "However, metformin, which is known to increase insulin resistance, activated the transcription of both BACE-1 and APP, potentially explaining its unsatisfactory therapeutic effect on the cognitive impairment when used alone." (PMID 40076550, 2025). "Positive correlations observed between elevated IL-6 levels, as a key interleukin in the inflammation process and BACE1, suggest a potential relationship between inflammation and BACE1, although this pathway was not altered in SS cognitive impairment." (PMID 40748886, 2025). "Similarly, inhibiting beta-site APP cleaving enzyme 1 (BACE1) palmitoylation reduces Aβ production and alleviates cognitive deficits." (PMID 40848510, 2025). "When 25 mg/kg per day and 100 mg/kg per day for 4 months were administered by gavage in the AD transgenic mice at the age of 2 months, cognitive impairment was mitigated without increasing BACE1 levels." (PMID 33652858, 2021).
Cognitive impairment (continued). "The first study analyzed BACE1 CSF concentrations and activity in a pooled cohort of cogntively healthy control (HC) individuals, clinically diagnosed patients with AD dementia (ADD), and individuals with mild cognitive impairment (MCI)." (PMID 33066807, 2020). "Meanwhile, the continuous upregulation of BACE1 further increases Aβ accumulation, leading to a more severe ERS, thus forming a vicious cycle that further contributes to neurodegenerative disorders and cognitive impairments." (PMID 33330477, 2020). "Next, the effects of BACE1 inhibitor infusion were examined in a mouse model overexpressing human APP, the hAPP23 mouse, which has higher expression of APP than hAPPSw, and exhibits early cognitive impairment and extensive Aβ pathology (at 3–6 months)." (PMID 32407295, 2020). "BACE1 is not only a dominant enzyme in Aβ synthesis from APP but also functions as an aspartic protease with altered enzymatic activity and protein expression in the brain early in the development of mild cognitive impairment." (PMID 28851397, 2017). "Other work reported a reduction in Aβ, amyloid deposition, and amelioration of cognitive deficits in 5XFAD/BACE1+/− mice, but did not differentiate between the sexes." (PMID 25567526, 2015). "The research reveals that the anticancer agent 6‐thioguanosine (6‐TG) markedly diminishes BACE1 expression without eliciting cytotoxicity while enhancing microglial phagocytic activity, and ameliorate cognitive impairments with reducing Aβ accumulation in AD mice." (PMID 39755927, 2025). "Moreover, plasma GLP-1 levels decrease in APP23/PS45 mice and negatively correlate with brain Aβ load in AD patients, while an GLP-1R agonist improves cognitive impairment and lowers Aβ/β-CTF by reducing BACE1 expression in the hippocampus/cortex of APP23/PS45 mice." (PMID 41446639, 2025). "Moreover, fenofibrate could decrease the serum Kallistatin level, BACE1, Aβ, and phosphorylated tau of KAL-TG mice, leading to alleviating memory and cognitive impairment." (PMID 40762561, 2025). "Although further studies on the cleavage of Np by BACE1 were not conducted, an attractive hypothesis is that increased neuroplastin cleavage by BACE1 could result in the cognitive deficits observed in AD." (PMID 34680901, 2021). "Furthermore, the modulating effect of TCA on BACE1 levels was associated with the upregulation of PPARγ, SIRT1, and PGC1α, negative regulators of BACE1 that ultimately led to the improvement in cognitive impairment without any effects in the WT mice." (PMID 32599846, 2020). "However, the effects of EE on stress-related cognitive impairment and Bace1 expression have not been well studied." (PMID 27404286, 2016). "Moreover, the relationships between amyloid burden and cognitive impairment are not sufficiently well understood to determine the stage of AD that BACE1 inhibitor treatment would be most effective." (PMID 25621019, 2014). "However, platelet BACE1 is not correlated with cognitive impairment in AD patients, suggesting that platelet BACE1 activity may precede AD neuropathology." (PMID 39757022, 2025). "Cognitive impairment was found in MI rats, along with dendritic spine loss, blood-brain barrier (BBB) breakdown, brain mitochondrial dysfunction, and decreased mitochondrial and increased glycolysis metabolism, without the alteration of APP, BACE-1, Tau and p-Tau proteins." (PMID 38362882, 2024). "As a reliable readout of subtle cognitive impairment that precedes symptom onset in standard memory tests, ALF is useful for objectively detecting cognitive benefits (if any) that may be produced by lower, physiologically relevant levels of BACE1 inhibition (~30% or even smaller)." (PMID 39081986, 2023). "Therefore, we hypothesized that exercise activated the PI3K/Akt signaling pathway in the hippocampus of APP/PS1 mice, decreased the expression level of BACE1 and correspondingly increased the level of UCHL-1, thereby improving cognitive impairment in the AD state." (PMID 36195875, 2022).